CDK4 (cyclin dependent kinase 4)
Diseases named in the same sentence as CDK4 in open-access papers (continued):
Sharing a sentence is not in itself a finding about the gene and the disease.
tumor (continued). "CDK4/6-targeted therapies have a complex network of immunomodulatory effects on tumor cells and their tumor microenvironment." (PMID 34395246, 2021). "As the patient had been progressive on combined immunotherapy, targeted therapy with combined MEK and CDK4/6 inhibition was initiated as recommended by the molecular tumor board." (PMID 33732653, 2021). "Gene expression analysis of MSL tumours showed that they retained RB1 while displaying significantly lower CDK4 and CDK6 expression levels, which means they have a pre-set level for reduced cell cycle progression." (PMID 34316709, 2021). "As an example, it has been shown that CDK4/6 inhibitors result in tumor-expression of cytokines that promote T cell recruitment." (PMID 34135901, 2021). "Mesenchymal-like cells with an inducible shRNA targeting CDK4 showed a greater reduction in tumor cell growth, with suppression of phosphorylated RB compared with epithelial-like 393P cells." (PMID 34309585, 2021). "In this model, CDK4/6 inhibition showed synergistic tumor suppression when combined with daratumumab." (PMID 35127532, 2021). "Palbociclib is a selective CDK4/6 inhibitor that restricts tumor growth in preclinical models of HCC." (PMID 34722778, 2021). "CDK4/6 inhibitors not only induce growth arrest of tumor cells, but also enhance T cell-mediated anti-tumor immunity." (PMID 34248938, 2021). "PI3Kα and CDK4/6i’s elicited cell cycle arrest, apoptosis, and calreticulin exposure and enhanced tumor immunogenicity in a syngeneic triple-negative BC model." (PMID 33161487, 2021). "Primary tumor tissues were collected at the end of the mouse experiments and stained for the CDK4 and MAPK signaling pathway markers." (PMID 34309585, 2021). "When compared to single therapies, combined PI3K and CDK4/6 inhibition, resulted in enhanced anti-tumour effects, including tumour regression." (PMID 34354223, 2021). "In view of this, AK2 has great potential for use in clinical diagnosis and prognosis of tumours based on monitoring of CDK4 biomarkers, while also holding promise as an intrabody-based anti-tumour therapy that acts by targeting intracellular CDK4." (PMID 34930213, 2021). "High zinc finger E-box binding homeobox 1 levels in mesenchymal tumor cells repressed p21, leading to perturbed CDK4 pathway activity." (PMID 34309585, 2021). "The anti-tumor mechanism of Abemaciclib is to inhibit the CDK4/6 pathway, which mediated drug resistance to anti-HER2 agents." (PMID 34490125, 2021). "The identification of molecules in EMPD tumor cells that correlate with prognosis, such as CDK4, should lead to the establishment of novel therapeutic approaches." (PMID 34395284, 2021). "Immunofluorescence assays on 393P, 393P-AZDR, and 344SQ cells revealed that a higher percentage of epithelial-like cells had nuclear p21 than mesenchymal-like cells, along with higher colocalization of CDK4 and p21 in epithelial-like tumor cells." (PMID 34309585, 2021). "c-Myc, as an oncogene, and its target genes, including eukaryotic translation initiation factor 4E (eIF4E) and Cyclin-Dependent Kinase 4 (CDK4), are silenced following the miR-145 upregulation, which leads to tumor suppression." (PMID 34307654, 2021). "Treatment of tumor-bearing mice with the CDK4/6 inhibitor palbociclib and an anti-PD-1 antibody resulted in improved survival compared with either treatment alone." (PMID 33921301, 2021). "But recent advances, including the first ileal NET mouse model as well as methods for culturing patient tumor samples, have been described and have already helped to identify IGF2 and CDK4 as two of the genetic drivers for this tumor type." (PMID 34680217, 2021). "p16(INK4A) is involved in the tumour cell intrinsic regulation of cell cycle progression by blocking the activity of CDK4/6." (PMID 32330367, 2021).
tumor (continued). "Upon growth factor stimulation, the CDK4/6 complex binds to cyclin D1 and phosphorylates the retinoblastoma protein (RB), a master regulator of cell cycle entry and critical tumor suppressor." (PMID 33809714, 2021). "Clinical studies have demonstrated that CDK4/6 inhibitors alone present drug activity in some tumor models as observed in liposarcoma." (PMID 34440587, 2021). "Downregulation of miR-9 was observed in tumor tissues and forced expression of the same promoted apoptosis via targeting cyclin-dependent kinase 4/6 (CDK4/6) proliferative pathways." (PMID 33806361, 2021). "In MMTV-Erbb2 breast, MC38 colon, and B16-F10 melanoma tumor models, CDK4/6 inhibition led to a decrease in total numbers of CD3+ tumor infiltrating T cells, encompassing CD8+ T cells and Granzyme B+ and IFNγ+ cells." (PMID 34025662, 2021). "P16INK4A acts as not only a surrogate marker of HPV infection but also a tumor suppressor gene, which regulates the cell cycle by specifically inhibiting cyclin D/CDK4/6 activity." (PMID 34521948, 2021). "Although CDK4/6 can bind with cyclin D1, resulting in Rb hyperphosphorylation, palbociclib can block Rb phosphorylation and prevent E2F1 release by separating CDK4/6–cyclin D1 complexes, resulting in G1 phase arrest and inhibit tumor growth." (PMID 34395246, 2021). "In fact, 393P tumor cells appeared to have slightly greater growth rate with CDK4 knockdown than the control cells and continued RB phosphorylation." (PMID 34309585, 2021). "Administration of CDK4/6i inflames the TIM of BC by reversing “cold” tumors to “hot” tumor by repressing immunosuppressive cells and potentiating the infiltration and function of antitumor immune cells." (PMID 33413549, 2021). "CDK4/6 inhibitors function as ATP competitive inhibitors, while they intervene in the phosphorylation and inactivation of retinoblastoma, a key tumor suppressor fundamental in cell cycle and the inactivation of FOXM-1." (PMID 33732735, 2021). "As a consequence, CDK4/6i increased antigen presentation by tumor cells and reduced tumor infiltration by immunosuppressive regulatory T cells." (PMID 34204543, 2021). "To determine the anti-tumor efficacy of CDK4/6/HSP90 dual inhibition in vivo, we used HT29 cancer cells in a xenograft mouse model." (PMID 34686682, 2021). "This suggests that the effects of CDK4/6 inhibitors predominantly relate to T cell-extrinsic mechanisms, including increased antigen-presentation capacity of tumor cells or APCs that boost anti-tumor immunity." (PMID 34248938, 2021). "CDK4/6 inhibitors, designed to inhibit uncontrolled cellular proliferation, made tumor types with better efficacy and few adverse effects in which CDK4/6 plays a key role in G1-to-S-phase cell-cycle transition to be targeted." (PMID 34395246, 2021). "Within the tumor microenvironment, the effects of CDK4/6i on the T cell infiltrate appear to vary depending on the tumor model and treatment schedule used." (PMID 34025662, 2021). "The first product discovered, p16INK4a (Inhibitor of CDK4/6), is a cyclin dependent kinase (CDK) inhibitor that enforces RB1 tumor suppressive activity by specifically inhibiting CDK4 and CDK6." (PMID 34680266, 2021). "In the MVA, PR-negative tumour (HR, 2.37; 95% CI, 1.45–3.88; p = 0.001) and CDK4/6i dose reduction (HR, 1.51; 95% CI, 1.06–2.16; p = 0.022) predicted worse PFS." (PMID 34207443, 2021). "Upon treatment with CDK4/6i, the abundance of tumor-infiltrating immunosuppressive myeloid cells was significantly reduced in breast tumors along with decreased levels of IL-6, IL-10, and IL-23, and these cytokines can depress TH1 response." (PMID 33413549, 2021). "Mice with existing tumors were treated with trilaciclib, a CDK4/6 inhibitor approved for metastatic non-small cell lung cancer, and tumor volume was subsequently measured." (PMID 34830174, 2021).
tumor (continued). "In fact, blood samples of 34 patients from the MONALEESA-2 trial, who progressed after CDK4/6 inhibitor therapy, were further investigated for circulating tumor DNA (ctDNA) using next-generation sequencing." (PMID 33535617, 2021). "Consistently, we found that CDK4/6 expression levels were negatively correlated with the infiltration of most immune cells in the Tumor IMmune Estimation Resource (TIMER) database." (PMID 35095879, 2021). "Collectively, these results indicated that licorice is likely to induce tumor cells arrested at G0/G1 growth phase by down-regulating CDK4-Cyclin D1 complex." (PMID 34641869, 2021). "Clear evidence does exist that tumor cells exposed to CCND1/CDK4 and CDK6 complex inhibitor increase their sensitivity to IR thanks to the induction of sustained DNA double-strand breaks (DSB)." (PMID 34445095, 2021). "The anti-proliferative effects of Clo and Fenti occur also in 3D cancer models (i.e., tumor spheroids) and in a synergic manner with the CDK4/CDK6 inhibitors palbociclib and abemaciclib." (PMID 33805656, 2021). "In turn, does cyclin D mediate all functions of AMBRA1 in tumor suppression and CDK4/6 inhibitor resistance?" (PMID 34413284, 2021). "TNBCs are a highly proliferative group of tumours enriched for high expression of cell-cycle genes, although they are considered to be resistant to CDK4/6 inhibitors." (PMID 34396843, 2021). "Palbociclib inhibited endothelial cell proliferation and tumor angiogenesis by disrupting the CDK4/6–cyclin D complex, thus the miR200b/QKI/CCND1 axis." (PMID 34439268, 2021). "A previous study reported that selective CDK4 inhibitors can induce tumor cell cycle arrest and promote anti-tumor immunity." (PMID 34120619, 2021). "In this RB1 wild-type tumor, the biallelic loss of CDKN2A was potentially targetable with CDK4/6 inhibitors." (PMID 33580196, 2021). "In vitro treatment of HCT116 colon tumor cell line with CINK4 prevented their cell growth by reducing Cyclin D/CDK4 complexes and Rb phosphorylation." (PMID 35002699, 2021). "In agreement, BTYNB impaired tumor cell vitality in strong synergy with the CDK4/6 inhibitor Palbociclib." (PMID 33829040, 2021). "In summary, designing and construction of human anti-CDK4 scFvs will likely facilitate future studies to understand CDK4 functions in normal and tumour cells, while also leading to development of key anti-cancer drugs that target CDK4." (PMID 34930213, 2021). "One of the most well-defined mechanisms by which CDK4/6i augments anti-tumor immunity is through enhancing the immunogenicity of tumor cells." (PMID 34025662, 2021). "We sought to understand the mechanisms behind infigratinib‐induced tumour cell differentiation and resistance and to explore the potential of adding the CDK4/6 inhibitor ribociclib to prolong cell differentiation." (PMID 33179425, 2021). "As G1-S transition overactivation occurs in the majority of malignant tumors, inhibitors of CDK4 and cyclin E1 have emerged as candidate drugs for tumor treatment." (PMID 33937074, 2021). "There are currently over 200 clinical trials ongoing with CDK4/6 inhibitors across multiple tumor types, including breast, lung, ovarian, colorectal, and prostate cancers." (PMID 33807608, 2021). "Immunohistochemistry staining of tumor tissues showed that aminoquinol treatment significantly reduced the expressions of Rb, CDK4, CDK6, PI3K, pho-AKT and pho-mTOR, as compared to the control group." (PMID 34335258, 2021). "After more time passes, these cells would be the ones that compose the tumor in a patient, since they are the ones that can survive in the presence of the CDK4/6 inhibitor." (PMID 34830174, 2021).
tumor (continued). "Hyperactivation of Ras-MEK-ERK signaling is another way tumor cells acquire resistance to CDK4/6 inhibitor therapy as the pathway converges on RB1." (PMID 33456709, 2021). "Findings from a preclinical study showed that CDK4/6 inhibitors combined with anti-PD-L1 therapy led to tumor regression in animal cancer models." (PMID 34026622, 2021). "A recent report also validated that CDK4/6 inhibitors markedly suppressed the proliferation of regulatory T cells (Tregs) and promoted cytotoxic T cell-mediated clearance of tumor cells in breast cancer." (PMID 35095879, 2021). "CDK4/6 has shown inhibition in PIK3CA-mutant xenograft tumor models and CDK4/6 inhibition has shown growth retardation." (PMID 34440080, 2021). "A previous study had shown that p21 can interfere with the binding of small inhibitors to CDK4 complex, as we observed in WT epithelial tumor cells and in p21-overexpressing mesenchymal cells." (PMID 34309585, 2021). "The presence of defective cyclin D, CDK4 and CDK 6 proteins, or mutations in their genes can promote both tumor initiation and progression." (PMID 34445095, 2021). "In a preclinical study, the combination between MEK and CDK4/6 inhibitors prevents tumor cell proliferation by promoting senescence in vitro, without any significant change in apoptosis in PDAC cells." (PMID 34440587, 2021). "A novel anti-CDK4 scFv antibody that can recognise and interact specifically with recombinant human CDK4 and endogenous CDK4 in tumour cells was expressed and purified successfully." (PMID 34930213, 2021). "We utilized functional shRNA screens, in in vitro and in vivo models, to identify and validate an increased dependence of mesenchymal tumor cells on cyclin-dependent kinase 4 (CDK4) for survival, as well as a mechanism of resistance to MEK inhibitors." (PMID 34309585, 2021). "Mesenchymal-like tumor cells underwent greater apoptosis in response to CDK4 inhibitors, while epithelial-like tumor cells were highly sensitive to MEK inhibition." (PMID 34309585, 2021). "Dalpiciclib (SHR6390) is a novel inhibitor of cyclin-dependent kinase 4/6 which demonstrated promising anti-tumor potency in preclinical models." (PMID 33845905, 2021). "Compared with the NC tumours, the protein level of CD11b and CD14 greatly increased in ZEB1 knock‐down tumours, while the expression of cyclin D1, cyclin A2, p‐Rb and CDK4 was markedly decreased in ZEB1 knock‐down tumours." (PMID 33960640, 2021). "We also demonstrated that HGF, rich in the tumor microenvironment in the liver, reduces the effect of CDK4/6 inhibitor in UM." (PMID 33806615, 2021). "The potency of CDKN2B/p15INK4B in tumor suppression relies on its strong binding via key N-terminal residues to and inhibition of CDK4/CDK6." (PMID 33824349, 2021). "Unexpectedly, however, CDK4/6 inhibition increased PD-L1 protein stability in tumor cells by preventing proteasome-mediated PD-L1 degradation." (PMID 33807608, 2021). "CDK4/6 inhibitors not only induce cell cycle arrest, but also enhance tumor immunogenicity, which provides the rationale for combination with ICIs." (PMID 34026622, 2021). "Nevertheless, endocrine treatment-sensitive cells showed durable tumor growth inhibition with both fulvestrant plus AKTi or fulvestrant plus CDK4/6i." (PMID 34433817, 2021). "In concordance with the in vitro data, the expression of both cyclinD1 and Cdk4 was significantly reduced in shOrai3 tumor protein samples in comparison to that in shNT tumor lysates." (PMID 34885048, 2021). "Immunofluorescence staining of tumor cells demonstrated an activated CDK4/RB axis with a higher percentage of 344SQ tumor cells with positive nuclear staining for phosphorylated CDK4 (phospho-CDK4) and phospho-RB and a stronger staining for total CDK4." (PMID 34309585, 2021). "In this review we focused the attention on the last five years progress in the optimization of clinically approved CDK4/6 inhibitors, primarily tested for their BC anti-tumor activity." (PMID 33803309, 2021).
tumor (continued). "CDK4/6i induction of antitumor immunity and immune checkpoint expression in tumor cells and T cells strongly suggest the ability of CDK4/6i to skew “cold” type BC into “hot” tumor, implying their potential of being combined with ICBs." (PMID 33413549, 2021). "Nobiletin downregulated the SKP2-p21/p27-CDK2 axis to inhibit tumor progression and showed synergistic tumor inhibition effects with the CDK4/6 inhibitor, palbociclib, on RCC, which indicates a potential new therapeutic strategy." (PMID 33628597, 2021). "We verified that the cell cycle position of MAPK-inhibited tumor cells can be manipulated by downregulating Cyclin D2 or blocking CDK4/6 activity via Palbociclib." (PMID 33821796, 2021). "As we previously discussed, nobiletin inhibited tumor progression by regulating the SKP2-p21/p27-CDK2 axis, and the insensitivity of the CDK4/6 inhibitor, palbociclib, was associated with higher SKP2 levels in RCC cells." (PMID 33628597, 2021). "We reported the G0/G1 growth phase cycle arrest of tumor cells induced by licorice is related to the down-regulation of CDK4-Cyclin D1 complex, which subsequently led to an increased protein abundance of PD-L1." (PMID 34641869, 2021). "We employed a genetic approach to confirm the dependency of mesenchymal cell–like tumor cells on CDK4 for survival." (PMID 34309585, 2021). "Yet, the presence of RB1 is crucial for exerting therapeutic effects of CDK4/6i’s and constitutes an already proven biomarker in other tumor entities." (PMID 33161487, 2021). "The patient with metastatic melanoma that achieved a PR had a tumor with molecular alterations (NRAS mutation and copy-number loss at the INK4 locus) that induced aberrant CDK4 and CDK6 activation." (PMID 34071228, 2021). "The relationship between CDK4 gene performance and tumor survival and prognosis was also investigated in this paper." (PMID 34422248, 2021). "Tumor thickness and regional lymph node metastasis were excluded from the model because they strongly correlated with CDK4 expression and TNM stage." (PMID 34395284, 2021). "Such mutation can renders CDK4 insensitive to INK4 inhibitors (e.g., p16INK4A) through preventing their binding, and induce development of multiple types of tumor in knock-in mouse model." (PMID 34249677, 2021). "Previous study has revealed that pharmacological inhibitors of CDK4/6 not only induce tumor cell cycle arrest but also promote anti-tumor immunity." (PMID 33557163, 2021). "In CDK4/6i-treated patients, ctDNA has been exploited to detect biomarkers of de novo resistance, to assess dynamics of genomic alterations during CDK4/6i administration and to evaluate biomarkers of acquired resistance at the time of tumor progression." (PMID 34072070, 2021). "These experimental results lay the foundation for subsequent studies based on internalisation of scFv antibodies in order to elucidate the function of CDK4 and target CDK4 within tumour cells." (PMID 34930213, 2021). "Novel approaches are being explored, including examination of multiple genetic alterations in circulating cell-free tumor DNA in liquid biopsies from ABC patients with disease progression on combined CDK4/6i and ET treatment." (PMID 34771560, 2021). "On the other hand, CDK4/6 inhibitors alone and in combination have also been reported to influence the tumor microenvironment and exert immunogenic effects." (PMID 33807122, 2021). "First, we find that CDK4/6 are overexpressed in a variety of tumor tissues, including OC, and that high expression of CDK4/6 is associated with a poor prognosis in OC patients." (PMID 35095879, 2021). "Inhibiting or downregulating the expression of CDK2 and CDK4 delays or inhibits cell cycle progression and reduces tumor proliferation and metastasis." (PMID 34582363, 2021). "The hope behind this is that the other drugs being included will help to overcome the tumor’s resistance mechanism and allow for the CDK4/6 inhibitor to have its efficacy restored." (PMID 34830174, 2021).